DZIP1 (DAZ interacting zinc finger protein 1)
Description:
Molecular adapter that recruits protein complexes required for cilium assembly and function to the cilium basal body. At the exit of mitosis, localizes to the basal body and ciliary base of the forming primary cilium where it recruits and activates RAB8A to direct vesicle-mediated transport of proteins to the cilium (By similarity). Also recruits the BBSome, a complex involved in cilium biogenesis, by bridging it to PCM1 at the centriolar satellites of the cilium. It is also required for the recruitment to the cilium basal body of the intraflagellar transport (IFT) machinery as well as the ciliary appendage proteins CEP164 and NINEIN (By similarity). Functions as a regulator of Hedgehog signaling both through its role in cilium assembly but also probably through its ability to retain GLI3 within the cytoplasm (By similarity). It is involved in spermatogenesis through its role in organization of the basal body and assembly of the sperm flagellum. Also indirectly involved in heart development through its function in ciliogenesis.
Synonyms: DZIP; KIAA0996; DZIPt1; MMVP3; MVP3; SPGF47
Tractability: PROTAC: ubiquitination databases record sites on it.
Gene: Protein-coding gene on chromosome 13 (95,578,202 to 95,644,740, reverse strand). Ensembl gene ENSG00000134874.
Subcellular location: Cytoplasm, cytoskeleton, cilium basal body; Cytoplasm, cytoskeleton, microtubule organizing center, centrosome, centriolar satellite; Cytoplasm, cytoskeleton, microtubule organizing center, centrosome, centriole; Nucleus; Nucleus speckle; Cytoplasm
Subcellular location (Human Protein Atlas): Basal body; Centrosome; Nucleoplasm; Cytosol
Pathways (Reactome):
Signal Transduction: Hedgehog 'on' state
Gene Ontology:
Molecular function: BBSome binding; molecular adaptor activity; protein binding; protein sequestering activity
Biological process: ciliary basal body organization; cilium assembly; germ cell development; heart development; protein-containing complex localization to centriolar satellite; sperm flagellum assembly; spermatogenesis; positive regulation of protein localization to cilium
Cellular component: centriolar satellite; centriole; centrosome; ciliary basal body; cytoplasm; cytosol; nucleoplasm; nucleus; nuclear speck; ciliary base; ciliary transition fiber
Genetic constraint (gnomAD): Loss-of-function variants: 82 observed, 97.6 expected, observed/expected ratio (o/e) 0.84, 90% interval 0.7 to 1.01. The upper end of that interval is the gene's LOEUF score, 1.01, which puts it in group 4 of 6, group 1 being the genes least tolerant of losing a copy. Missense variants: 966 observed, 1,012.8 expected, observed/expected ratio (o/e) 0.95, 90% interval 0.9 to 1.01. Synonymous variants: 369 observed, 377.07 expected, observed/expected ratio (o/e) 0.98, 90% interval 0.9 to 1.07.
Homologues: Orthologues: chimpanzee DZIP1 (99% identical), macaque DZIP1 (94% identical), dog DZIP1 (78% identical), rabbit DZIP1 (75% identical), guinea pig DZIP1 (73% identical), pig DZIP1 (69% identical), mouse Dzip1 (67% identical), rat Dzip1 (66% identical), zebrafish dzip1 (31% identical), tropical clawed frog dzip1 (31% identical), rat Dzip1-ps1 (24% identical). Paralogues in human: DZIP1L (27% identical), RILPL1 (9% identical), RILP (6% identical), RILPL2 (4% identical).
Diseases named in the same sentence as DZIP1 in open-access papers:
DZIP1 is named in the same sentence as 16 diseases in open-access papers, as found by Europe PMC text mining. Sharing a sentence is not in itself a finding about the gene and the disease. The quoted sentences say what the papers report.
Azoospermia (3 papers, 2014 to 2024). Absence of any measurable level of sperm,whereby spermatozoa cannot be observed even after centrifugation of the semen pellet. "DZIP1 encodes a DAZ (a protein deleted in azoospermia) interacting protein, there is strong evidence that the DAZ and a closely related homolog, DAZL (DAZ-like), are required in early germ cell development to maintain initial germ cell populations." (PMID 37854191, 2023).
mitral valve prolapse (3 papers, 2021 to 2024). A fairly common and often benign valvular heart disorder characterized by redundancy or hooding of mitral valve leaflets so that they prolapse into the left atrium, often causing mitral regurgitation. "We recently identified mutations in the DZIP1 gene in multiple families with inherited non syndromic mitral valve prolapse." (PMID 33811421, 2021). "Crucially, the authors employed both a conditional knock-out of Ift88, as well as a mouse mutant in the Dzip1 gene, bearing a DZIP1 mutation seen in patients with mitral valve prolapse, thereby showing a brilliant complementary usage of the two species to elucidate CHDs at the translational level." (PMID 35741008, 2022). "During the valve development, premature loss of primary cilia due to a missense mutation of a ciliary gene DZIP1 or by IFT88 conditional knockout in the valve interstitial cells induces an enhanced ECM synthesis, resulting in dysmorphic leaflets and, eventually, in mitral valve prolapse in adult." (PMID 38816374, 2024).
Alzheimer disease (1 paper, 2012). A progressive, neurodegenerative disease characterized by loss of function and death of nerve cells in several areas of the brain leading to loss of cognitive function such as memory and language. "Taken together, our results provide strong evidence to support our hypothesis that knocking down protein dZip1 may mitigate Aβ pathology and Aβ-dependent behavioral defects in a Drosophila model of Alzheimer's disease." (PMID 22570624, 2012).
breast carcinoma (1 paper, 2014). "Indeed, DZIP1-knockdown in breast cancer cell lines promotes cell growth." (PMID 24993635, 2014).
co-infection (1 paper, 2025). "Regarding the co-infection of cells by E. coli and S. aureus, the unique genes of ES2 are DZIP1 and SMTNL2; the unique genes of ES3 are ALDH4A1, DNASE1L1, FAM227A, and KAT2B; and ES1 has 143 unique genes." (PMID 40771952, 2025).
cancer (4 papers, 2014 to 2025). A tumor composed of atypical neoplastic, often pleomorphic cells that invade other tissues. "DZIP1 is a regulator of hedgehog signalling, though recent bioinformatic analysis has indicated potential associations between expression levels of DZIP1 and survival in human cancers." (PMID 41272979, 2025). "In this scenario, the vast majority of CpG island promoter methylated genes represent passenger events with only a few true cancer driving events found in each case; in this context, DZIP1, COL4A2, L3MBTL4, IRX1 and RASSF10 are named as likely candidates." (PMID 25468711, 2015). "DZIP1 is also involved in the regulation of Hedgehog signaling, a pathway activated in several types of human cancers." (PMID 24993635, 2014).
tumor (3 papers, 2007 to 2015). "In this analysis, we identified subtype‐specific events for Epi‐LumB tumors involving either DNA copy number loss or CpG promoter methylation over DZIP1, TNFSF11, ZIC5, COL4A2, COL4A1 and PCDH8 indicating candidate tumor suppressor genes." (PMID 25468711, 2015). "By using data on DNA copy number changes, we identified genes of potential interest as tumor suppressors in the development of Epi‐LumB and Epi‐Basal tumors, including DZIP1 and COL4A2 (Epi‐LumB) and TENC1 (Epi‐Basal)." (PMID 25468711, 2015). "DZIP1 has recently been identified as a putative tumor suppressor involved in controlling cell proliferation." (PMID 24993635, 2014).
DZIP1 also shares sentences with these, for which no sentence is quoted: ciliopathy (3 papers); Infertility (2); coloboma (1); colorectal cancer (1); Failure to thrive (1); gastric cancer (1); Hypertension (1); lung carcinoma (1); renal cell carcinoma (1).